SGK2 (serum/glucocorticoid regulated kinase 2)
Description:
Serine/threonine-protein kinase which is involved in the regulation of a wide variety of ion channels, membrane transporters, cell growth, survival and proliferation. Up-regulates Na(+) channels: SCNN1A/ENAC, K(+) channels: KCNA3/Kv1.3, KCNE1 and KCNQ1, amino acid transporter: SLC6A19, glutamate transporter: SLC1A6/EAAT4, glutamate receptors: GRIA1/GLUR1 and GRIK2/GLUR6, Na(+)/H(+) exchanger: SLC9A3/NHE3, and the Na(+)/K(+) ATPase.
Synonyms: H-SGK2; dJ138B7.2
Tractability: Small molecule: a high-quality ligand is known; it belongs to a druggable protein family. PROTAC: ubiquitination databases record sites on it; a small molecule that binds it is known.
Target class: AGC protein kinase group; AGC protein kinase SGK family; Enzyme; Kinase; Protein Kinase
Gene: Protein-coding gene on chromosome 20 (43,558,968 to 43,588,237, forward strand). Ensembl gene ENSG00000101049.
Subcellular location: Cytoplasm; Nucleus
Subcellular location (Human Protein Atlas): Nucleoplasm
Pathways (Reactome):
Transport of small molecules: Stimuli-sensing channels
Gene Ontology:
Molecular function: potassium channel regulator activity; protein binding; protein serine/threonine kinase activity; sodium channel regulator activity; ATP binding; protein kinase activity; protein serine kinase activity
Biological process: intracellular signal transduction; positive regulation of transporter activity; protein phosphorylation
Cellular component: nucleoplasm; cytosol; cytoplasm; nucleus
Genetic constraint (gnomAD): Loss-of-function variants: 30 observed, 40.64 expected, observed/expected ratio (o/e) 0.74, 90% interval 0.55 to 1. The upper end of that interval is the gene's LOEUF score, 1, which puts it in group 4 of 6, group 1 being the genes least tolerant of losing a copy. Missense variants: 382 observed, 448.65 expected, observed/expected ratio (o/e) 0.85, 90% interval 0.78 to 0.93. Synonymous variants: 142 observed, 174.91 expected, observed/expected ratio (o/e) 0.81, 90% interval 0.71 to 0.93.
Homologues: Orthologues: macaque SGK2 (98% identical), chimpanzee SGK2 (97% identical), pig SGK2 (95% identical), guinea pig SGK2 (94% identical), mouse Sgk2 (94% identical), rat Sgk2 (93% identical), dog SGK2 (86% identical), tropical clawed frog sgk2 (75% identical), zebrafish sgk2a (73% identical), Caenorhabditis elegans sgk-1 (50% identical). Paralogues in human: SGK1 (71% identical), SGK3 (68% identical), MAST1 (36% identical), MAST3 (35% identical), MAST2 (35% identical), MAST4 (35% identical), LATS2 (33% identical), LATS1 (32% identical), DMPK (30% identical), MASTL (30% identical), STK32B (29% identical), STK32A (29% identical), and 1 more.
Diseases named in the same sentence as SGK2 in open-access papers:
SGK2 is named in the same sentence as 34 diseases in open-access papers, as found by Europe PMC text mining. Sharing a sentence is not in itself a finding about the gene and the disease. The quoted sentences say what the papers report.
cervical cancer (4 papers, 2015 to 2026). A primary or metastatic malignant neoplasm involving the cervix. "PAK3 and SGK2 were recently associated with the survival of HPV+ cervical cancer cells." (PMID 25615606, 2015). "The p21-activated kinase 3 (PAK3) and the serum and glucocorticoid-induced kinase 2 (SGK2) have been previously proposed as essential kinases for human papillomavirus positive (HPV+) cervical cancer cell survival." (PMID 25615606, 2015). "It was proposed that the p21-activated kinase 3 (PAK3) and the serum and glucocorticoid-induced kinase 2 (SGK2) were essential for HPV positive (HPV+) cervical cancer cell survival." (PMID 25615606, 2015). "In summary, we have validated the function of PAK3 and SGK2 lentiviral shRNAs in the knockdown of PAK3 and SGK2 gene expression, and also observed viability loss of HPV+ cervical cancer cells (HeLa and CaSki) mediated by the lentiviral shRNAs." (PMID 25615606, 2015). "Nevertheless, the suggested importance of PAK3 or SGK2 in the survival of HPV+ cervical cancer cells elevated our interest in these kinases as potential targets for HPV drug intervention." (PMID 25615606, 2015). "The authors found that the proliferation/viability of HPV+ cervical cancer cells, CaSki, HeLa and SiHa, was selectively inhibited by multiple PAK3 and SGK2 shRNAs." (PMID 25615606, 2015). "To determine whether HPV+ cervical cancer cells are specifically vulnerable to PAK3 and SGK2 shRNAs, we investigated four control lentivirus shRNA vectors that do not target human genes (Luc, EGFP, T-GFP and NT shRNAs) for their effect on the proliferation/ viability of HeLa and CaSki cells." (PMID 25615606, 2015). "Therefore, the lethality of PAK3 or SGK2 shRNAs to HPV+ cervical cancer cells did not appear related to the inhibition of PAK3 or SGK2 expression but rather through a non-specific RNAi effect." (PMID 25615606, 2015). "In this study, we demonstrate that the phenotypes of HPV+ cervical cancer cells induced by PAK3 or SGK2 shRNAs could not be rescued by complement expression of respective cDNA constructs." (PMID 25615606, 2015). "We observed that the phenotypes of HPV+ cervical cancer cells induced by various PAK3 and SGK2 shRNAs could not be rescued by complement expression of respective cDNA constructs." (PMID 25615606, 2015).
colon cancer (3 papers, 2009 to 2023). "Recent reports have demonstrated that SGK2 upregulation promotes the progression of metastasis in bladder, kidney, and colon cancers, but the relationship between SGK2 and PCa metastasis is unclear." (PMID 36720852, 2023).
hepatoma (3 papers, 2015 to 2020). "SGK2 expression was upregulated in hepatocellular carcinoma and its downregulation inhibits cell migration and invasion." (PMID 32998690, 2020). "In the human hepatoma cell line HepG2, Gotoh and Negishi found SGK2 dephosphorylation to contribute to the activation of drug-induced gluconeogenesis." (PMID 30390635, 2018). "Similar regulation by SGK2 was also observed in human hepatoma HepG2 cell-derived ShP51 cells that stably express human PXR15." (PMID 26392083, 2015).
bladder cancer (2 papers, 2020 to 2021). "SGK2 has been associated with hepatocarcinoma progression and bladder cancer cell proliferation, migration, and invasion." (PMID 32318098, 2020). "We found that a low expression of METTL14 (a m6A methyltransferase), SMPD4, and SGK2, but a high expression of ALKBH5 (a m6A de methyltransferase), LINC00482, and HIPK3, showed a tendency to associate with worse overall survival in bladder cancer patients." (PMID 34868913, 2021).
Cirrhosis (2 papers, 2022 to 2024). A chronic disorder of the liver in which liver tissue becomes scarred and is partially replaced by regenerative nodules and fibrotic tissue resulting in loss of liver function. "Network 2 was persistent in viral hepatitis, cirrhosis, and HCC, with three potential hub genes (FABP1, SGK2, and HNF4A)." (PMID 38302914, 2024). "To evaluate whether FABP1, SGK2, and HNF4A related to cirrhosis and HCC, we examined the methylation levels of these gene using the GSE60753 dataset." (PMID 35655171, 2022).
Hypertension (2 papers, 2018 to 2025). The presence of chronic increased pressure in the systemic arterial system. "Given that SGK1 has been implicated in renal sodium retention and associated with hypertension, these findings highlight the need for continued investigation into the potential roles of SGK2 in both placental function and maternal cardiovascular health." (PMID 41444673, 2025). "In contrast, there were no significant different in SGK2 and SGK3 mRNA in spleen among the four groups of mice, suggesting that neither of them may not be involved in AngII-induced hypertension." (PMID 30524295, 2018).
melanoma (2 papers, 2015 to 2023). A malignant, usually aggressive tumor composed of atypical, neoplastic melanocytes. "Recent studies have reported that inhibiting ferroptosis promotes the metastasis of breast cancer, clear cell renal cell carcinoma, and melanoma; therefore, we presumed that the increase of SGK2 in facilitating PCa metastasis may be mediated by inhibiting ferroptosis." (PMID 36720852, 2023).
prostate carcinoma (2 papers, 2023). A carcinoma that arises from epithelial cells of the prostate gland. "In the current study, we identified the essential role of serum/glucocorticoid regulated kinase 2 (SGK2) in promoting prostate cancer metastasis by inhibiting ferroptosis." (PMID 36720852, 2023). "SGK2 knockdown inhibited the metastatic capacity of prostate cancer cells in vivo and in vitro, while SGK2 overexpression inhibited ferroptosis and facilitated prostate cancer metastasis by phosphorylating the Thr-24 and Ser-319 sites of forkhead box O1 (FOXO1)." (PMID 36720852, 2023).
alcoholic hepatitis (1 paper, 2022). Acute hepatitis resulting from ingestion of alcohol. "Common changes in the methylation levels of FABP1, SGK2, and HNF4A from fibrosis to cancer were found in NAFLD, hepatitis virus, and alcoholic hepatitis." (PMID 35655171, 2022). "The overall findings indicate that the formation of DMR networks involving FABP1, SGK2, and HNF4A could cooperatively and/or synergistically affect fibrosis and carcinogenesis in advanced NAFLD and viral and alcoholic hepatitis." (PMID 35655171, 2022). "Thus, increased methylation of SGK2 may suppress abnormal cell growth in NAFLD as well as in viral and alcoholic hepatitis, while decreased methylation may facilitate cell growth and proliferation in HCC." (PMID 35655171, 2022).
gastric carcinoma (1 paper, 2015). A carcinoma that arises from epithelial cells of the stomach. "The knockdown of SGK2 protein was therefore evaluated in GTL16, a SGK2 high expression gastric carcinoma cell line." (PMID 25615606, 2015).
leukemia (1 paper, 2022). A malignant (clonal) hematologic disorder, involving hematopoietic stem cells and characterized by the presence of primitive or atypical myeloid or lymphoid cells in the bone marrow and the blood. "Interestingly, higher copy number of the imprinted genes L3MBTL1 and SGK2 at 20q13.12 was weakly associated with drug resistance, and their increased expression was associated with resistance to several agents in leukemia tumor samples from the Beat AML study." (PMID 36461044, 2022).
metastatic prostate carcinoma (1 paper, 2023). A carcinoma that arises from the prostate gland and has spread to other anatomic sites. "We found that the expression of SGK2 was higher in metastatic prostate cancer and predicted poor clinical outcomes." (PMID 36720852, 2023).
preeclampsia (1 paper, 2025). Preeclampsia is a hypertensive disorder of pregnancy that is characterized by new-onset hypertension with proteinuria presenting after 20 weeks of gestation, and depending on mild or severe forms may initially present with severe headache, visual disturbances, and hyperreflexia. "Notably, SGK2 expression was upregulated in placentas from male-bearing pregnancies affected by late-onset preeclampsia." (PMID 41444673, 2025).
renal carcinoma (1 paper, 2022). A carcinoma arising from the epithelium of the renal parenchyma or the renal pelvis. "SGK2 enhances the development of renal carcinoma by increasing ERK1/2 and AKT phosphorylation." (PMID 36176934, 2022).
viral hepatitis (1 paper, 2024). An acute or chronic inflammation of the liver parenchyma caused by viruses. "Network 2 contained 430 DMRs and was observed in viral hepatitis and HCC populations with three potential hub genes (FABP1, SGK2, and HNF4A)." (PMID 38302914, 2024). "Network 2 was observed in viral hepatitis and HCC, with three potential hub genes: fatty acid binding protein 1 (FABP1), serum/glucocorticoid regulated kinase 2 (SGK2), and hepatocyte nuclear factor 4 α (HNF4A)." (PMID 38302914, 2024).
cancer (9 papers, 2015 to 2026). A tumor composed of atypical neoplastic, often pleomorphic cells that invade other tissues. "In the CCK-8 assay, we observed that GPX4 overexpression promoted cancer cell growth, which was inhibited by low levels of SGK2." (PMID 36720852, 2023). "The increase of SGK2 reportedly promoted cancer progression." (PMID 36720852, 2023). "The previous study has reported that inhibited SGK2 could induce cell death in multiple types of cancer, which could play a new role in cancer treatment." (PMID 34575686, 2021). "In summary, the simultaneous low expression of PLK1, phosphoMet, SGK2, and SHC1 might be associated with the immune response and tumor cell survival, which could result in poor survival outcomes in cancer progression." (PMID 34575686, 2021). "Hence, we identified a new pathway that links autophagy to the survival of cancer cells under platinum treatment in which the druggable kinase SGK2 plays a central role." (PMID 32848212, 2020). "Being SGK2 a druggable kinase, amplified in a subset of EOC, for which inhibitors are already available our findings could have also an immediate translational relevance to improve the treatment and/or the quality of life of patients with PT-treatable, SGK2-expressing cancers." (PMID 32848212, 2020). "Starting from an unbiased loss-of-function screening that identified SGK2 as a druggable modulator of PT sensitivity in EOC cells, we characterized the role of this under-studied kinase in the control of autophagy, an escaping strategy activated by cancer cells to survive under PT treatment." (PMID 32848212, 2020). "PD-L1 up-regulated serum and glucocorticoid kinase 2 (SGK2), activated SGK2/β-catenin signaling pathway, and promoted the expansion of HCC cell epithelial-mesenchymal transition (EMT) and cancer stem cell (CSC)." (PMID 38155974, 2023). "SGKs, which consist of three isoforms, SGK1, SGK2, and SGK3, are critical mediators of AKT-independent signaling downstream of PDK1 and mTORC2 in cancer." (PMID 33960177, 2021). "It is interesting to note that although SGK2 inhibition transiently blocks autophagy also in untreated and Taxol-treated cells, this block did not result in toxic effects for normal or cancer cells, therefore supporting a specific role for SGK2 inhibition in the response to PT-induced death." (PMID 32848212, 2020). "Accordingly, SGK2 inhibition by GSK650394 did not affect Taxol induced cell death in MDAH cells, overall supporting the hypothesis that SGK2 kinase activity protects cancer cells from PT-induced death by regulating autophagy." (PMID 32848212, 2020).
tumor (8 papers, 2009 to 2025). "Copy number of both L3MBTL1 and SGK2 was associated with sensitivity to ispinesib mesylate in pancancer analysis of CCLE-GDSC tumor cell lines." (PMID 36461044, 2022). "The PLK1, PhosphoMet, SGK2, and SHC1 IHC staining of tumor samples from high-risk (disease progression) patients mostly showed low cytoplasmic expression, while tumor samples from low-risk (progression-free) patients mostly showed high cytoplasmic expression." (PMID 34575686, 2021). "Thus, we can stratify patients into high-risk groups and rapidly assess their outcomes based on the tumor expression of cytoplasmic PLK1, phosphoMet, SGK2, and SHC1." (PMID 34575686, 2021). "Accordingly, SGK2 could theoretically be a target for tumor suppressor-specific drug discovery." (PMID 35655171, 2022). "SGK2 and PLP1 appeared in the second position of biomarker classification, being active in the tumor samples of 69 patients and inactive in their respective controls." (PMID 32318098, 2020). "Many SGK2 isoforms were not expressed in a large number of AML, breast, ovarian, PDAC, and SCLC cell lines, as compared to a much smaller number of L3MBTL1 isoforms that were not expressed in these tumor histologies." (PMID 40414875, 2025).
infection (2 papers, 2008 to 2015). The state of being infected such as from the introduction of a foreign agent such as serum, vaccine, antigenic substance or organism. "Whether or not SGK2 or PRKWNK1 act on infection through the control of K+ concentration will require further investigation." (PMID 18989463, 2008). "All shRNAs tested in our experiments, including four SGK2 shRNAs and the control shRNA (NT shRNA), induced autophagic marker LC3B conversion when compared with the no infection control." (PMID 25615606, 2015).
SGK2 also shares sentences with these, for which no sentence is quoted: alcoholism (1 paper); breast carcinoma (1); clear cell renal cell carcinoma (1); enteroviral infection (1); head and neck cancer (1); liver cancer (1); liver fibrosis (1); lung adenocarcinoma (1); lung carcinoma (1); myeloid neoplasm (1); myeloproliferative neoplasm (1); Obesity (1); osteosarcoma (1); Type 2 diabetes (1); ulcerative colitis (1); viral infections (1).